GJB2 (gap junction protein beta 2)
Diseases named in the same sentence as GJB2 in open-access papers (continued):
Sharing a sentence is not in itself a finding about the gene and the disease.
deafness (continued). "Apart from GJB2 mutations, one kind of deafness-causing GJB6 mutation (⊿GJB6-D13S1854 or 232 kb del) was identified in 5 of 135 hearing-impaired individuals." (PMID 23554706, 2011). "Nonetheless, NGS for deafness is still useful in identifying babies with 2 mutated GJB2 alleles, for whom the genetic diagnosis is more straightforward." (PMID 21811586, 2011). "In summary, current data revealed that near half of the patients with NSHL carry deafness-causing mutation in GJB2, GJB3, GJB6, SLC26A4, or mtDNA 12SrRNA genes: 43.57% in China and 50.06% in other countries." (PMID 23554706, 2011). "Although the del(GJB6-D13S1830) mutation, through eliminating a cis-regulatory element of GJB2, provided an explanation for the deafness in as many as 30%–70% of affected GJB2 heterozygotes in some populations, the etiology remained unclear for the others." (PMID 21811586, 2011). "None of 35delG was detected in both the case and control groups of our country; however, the 35delG of GJB2 occupied the main cause of deafness in the Caucasian populations." (PMID 23554706, 2011). "The carrier frequencies of deafness-causing mutations in these patients were 35.55% in GJB2, 3.70% in GJB6, 15.56% in SLC26A4 and 8.14% in mitochondrial 12SrRNA, respectively." (PMID 23554706, 2011). "Testing for the GJB2 IVS 1+1 G to A mutation explained deafness in 1.89% of Chinese GJB2 monoallelic patients, and it should be included in routine testing of patients with GJB2 monoallelic pathogenic mutation." (PMID 21122151, 2010). "The deafness of individuals heterozygous for GJB2 mutations has been associated with in trans heterozygosity for GJB6 gene deletions." (PMID 21119891, 2010). "Digenic interactions are known to be an important cause of deafness in patients who carry a single mutation at the gap junction protein GJB2 (connexin 26) along with a deletion involving the functionally related GJB6 (connexin 30)." (PMID 21119891, 2010). "Testing for the GJB2 IVS 1+1 G to A mutation explained deafness in 1.89% of Chinese GJB2 monoallelic patients." (PMID 21122151, 2010). "Mutations in GJB2 gene are the leading cause of deafness in autosomal recessive inheritance, and the 35delG mutation is the most common in many ethnic groups." (PMID 20835527, 2010). "The most common molecular defects in nonsyndromic autosomal recessive deafness involve Connexin 26, a gap junction protein encoded by the GJB2 gene." (PMID 19744334, 2009). "The common GJB2 gene mutation (35delG) has been previously reported from Iranian patients that were affected with nonsyndromic autosomal recessive deafness." (PMID 20407643, 2009). "GJB2 mutations are responsible for deafness in 54% (7 out of 13) of the independent Russian families tested and the 35delG mutation was carried by 34.4% of the Russian alleles." (PMID 15790391, 2005). "We report here the results of a study based on patients presenting mainly prelingual deafness, with the mutation analysis of the GJB2 gene, the screening of the GJB6-D13S1830 deletion, and the study of five mitochondrial mutations involved in NSHI." (PMID 15790391, 2005). "Specific GJB2 mutation spectrums and different GJB2 contributions for deafness were observed for the two main ethnic groups studied here." (PMID 15790391, 2005). "As connexin 26 mutations are the most common cause of nonsyndromic recessive deafness, we sequenced the coding exon of GJB2 in affected individuals of Newfoundland family and found no mutation." (PMID 15447792, 2004). "During the analysis phase, the research team took altitude (low altitude, medium altitude, high altitude), ethnicity (Tibetan, Hui, Han, Salar, Tu, etc.), and genotype (15 loci of 4 common deafness-causing genes: GJB2, SLC26A4, mitochondrial 12SrRNA, and GJB3) as the core dimensions." (PMID 41734195, 2026).
deafness (continued). "The most prevalent deafness gene among Chinese neonates was the GJB2 c.235delC variant." (PMID 40283619, 2025). "Our study reported a pedigree with syndromic deafness caused by the GJB2 p.R184Q mutation, summarized the phenotype and inheritance mode of GJB2 p.R184Q reported previously, and confirmed that GJB2 p.R184Q is associated with both syndromic and non-syndromic deafness." (PMID 40336802, 2025). "In the Western Romanian population studied, the risk of deafness is given by pathogenic variants in 7 genes included in the panel: GJB2, USH2A, LOXHD1, SLC26A4, USH1C, COL4A4, COL4A3, present in almost 10% of the cohort, therefore representing a significant risk." (PMID 41303398, 2025). "For instance, gene replacement strategies for OTOF variations have reached the stage of clinical trials, and preclinical studies have demonstrated the potential of gene editing, antisense oligonucleotides, and RNA-based therapies for other genes associated with deafness, such as GJB2 and MYO7A." (PMID 41227304, 2025). "GJB2 is the most common deafness-causing gene in many ethnic groups." (PMID 38172427, 2024). "Mutations in GJB2 are responsible for recessive and dominant forms of deafness, but it was shown that the phenotypic spectrum of GJB2 mutations could be expanded to include epileptic manifestations." (PMID 38339022, 2024). "However, for common hereditary deafness genes such as GJB2 and SLC26A4, the mechanisms underlying deafness are intricate and lack an efficient mouse model capable of accurately simulating disease onset." (PMID 39556694, 2024). "In our case, initial screening for common deafness genes revealed only 1 variant in the GJB2 gene." (PMID 39151510, 2024). "This probably reflected in the phenotype: in fact, in our sample, the homozygosis pattern was associated with an average PTA of 63.70 ± 32.09 dB, probably because of the prevalence of the GJB2 (35delG/35delG) mutation, which is known to be associated with severe-to-profound deafness." (PMID 38397306, 2024). "In addition, large deletions spanning the GJB6 gene can cause deafness when present in trans with a single pathologic GJB2 mutation." (PMID 38397168, 2024). "GJB2 gene mutations account for up to 50% of non-syndromic deafness worldwide." (PMID 38397306, 2024). "Mutations in Gjb2 gene are responsible for the recessive deafness." (PMID 38715099, 2024). "The deafness family had compound heterozygous mutations in the Chr13:GJB2 gene (NM_004004.5; c.235delC [p.Leu79Cysfs] and c.299_300delAT [p.His100Argfs]); the details regarding cTB isolation (CFC178) and STR identification in this family are described in a previous study." (PMID 36810160, 2023). "In addition, we identified potentially novel deafness-associated genes Mpzl2 in IMCs and Tbx1 in MCs along with the known deafness-associated genes in IMCs (Kcnj10, Met, Mitf, Gjb6, Ednrb, and Gjb2) and in MCs (Kcnq1, Esrrb, Kcne1, Lrp2, Slc22a4, and Hgf)." (PMID 37322474, 2023). "Mutations in the GJB2 gene drive up to 50% of pre-lingual, recessive deafness." (PMID 37147621, 2023). "Loss of function variants in Gjb2 are a leading cause of inherited deafness worldwide, but the mechanisms responsible for these hearing deficits are unknown and there are no approved therapies to restore Cx26 function in these patients." (PMID 37368868, 2023). "More than 300 deafness mutations have been reported in GJB2 and GJB6." (PMID 35573684, 2022). "However, studies have shown that compound heterozygous or homozygous mutation allele of GJB2 c.109G > A has significantly variable penetrance and expressivity of deafness, associated with normal hearing to moderate progressive SNHL in humans." (PMID 36389375, 2022).
deafness (continued). "Deafness-causing mutations in the GJB2 gene may give rise to both non-syndromic and syndromic deafness, but are mostly autosomal recessive point mutations." (PMID 36204137, 2022). "In China, the predominant form of GJB2-related deafness involves the c.235delC mutation." (PMID 35457072, 2022). "Additionally, several GJB2 gene mutations cause autosomal dominant non-syndromic or syndromic deafness." (PMID 35457072, 2022). "The GJB2 mutations are the most common cause of deafness worldwide, including in Iran." (PMID 35101039, 2022). "EP reduction remains a controversial cause of Gjb2-related deafness." (PMID 35457072, 2022). "GJB2, the first gene to be implicated in nonsyndromic human deafness, was discovered in 1997." (PMID 36529647, 2022). "Nowadays, there are some advances in the treatment of GJB2 mutation-related deafness." (PMID 36187349, 2022). "Investigation of the most common gene causing deafness, the GJB2 gene, should be offered to families with children diagnosed with profound hearing loss, in addition to imaging (CT or MRI) according to the diagnostic suspicion and reality of each health facility." (PMID 36529647, 2022). "Additionally, a GJB2 gene mutation (Cx26 p.Asn14Lys) identified in a Dutch child led to a phenotype resembling Clouston syndrome accompanied with deafness." (PMID 35457072, 2022). "Several attempts have also been made to develop gene replacement strategies for the gap-junction protein connexin-26 (GJB2), defects of which cause one of the most common forms of deafness (30–50% of recessive forms of profound deafness in children from Mediterranean countries)." (PMID 34778871, 2021). "GJB2 c.235delC is the most common deafness-related pathogenic variant in the Chinese population, and reporting the phenotypic heterogeneity of GJB2 c.235delC homozygous cases is helpful throughout the genetic counselling procedure, and would contribute greatly to clinical practice." (PMID 33718389, 2021). "Although specific GJB2 mutations are involved in determining an autosomal dominant form of deafness (DFNA3) as well as various forms of syndromic deafness associated with skin disease; the great majority of mutations in this gene cause non-syndromic autosomal recessive hearing loss DFNB1." (PMID 34562878, 2021). "Therefore, this study aimed to investigate the common c.35delG, c.235delC, and c.167delT mutations in the connexin 26 (GJB2) genes in Iraqi deafness patients." (PMID 35126756, 2021). "Along with obviously pathogenic GJB2 variants severely truncating the Cx26 protein, a significant portion of deafness-associated GJB2 variants is represented by various single amino acid residue changes located in different regions of the Cx26 protein sequence." (PMID 33466560, 2021). "Particularly common pathogenic variants have been observed in certain other genetic diseases: e.g. p.Phe508del variant in CFTR in cystic fibrosis in Europeans, population-specific variants in HFE in hemochromatosis, and population-specific truncating variants in GJB2 in deafness." (PMID 33736665, 2021). "Compared with 20 variants in the four genes of traditional testing, the positive rate of expanded screening in 159 variants of 22 deafness related genes increased significantly (65.2% on average), including GJB2 increasing by 97.2%, SLC26A4 by 21%, and MT-RNR1 by 150%." (PMID 34276761, 2021). "IV2 was found to have a homozygous GJB2 c.71G>A variant, established as the cause of her deafness." (PMID 33632302, 2021). "This study presents a HL family GCUFAHL38, in which five different deafness genes (GJB2, SLC26A4, CDH23, MPDZ, KCNQ4) rare variants were co-segregating in different configurations, and thus further highlights the genetic complexity of hearing disorders in highly inbred families." (PMID 34946889, 2021).
deafness (continued). "The GJB2 mutation is one of the most common pathogenic factors related to genetic HL, and GJB2 usually is the first deafness gene to be evaluated during clinical diagnosis due to the observations that GJB2 is the most common human deafness gene in almost all populations studied so far." (PMID 32802038, 2020). "Our results showed that mutations in GJB2 account for over 25% of pathogenic causes in Chinese Han deaf patients, with expanded screening in other deafness-associated genes may help to further resolve cases with mono-allelic GJB2 mutations." (PMID 31992338, 2020). "GJB2, encoding connexin 26 (Cx26), is the most common deafness gene of hereditary deafness." (PMID 33505961, 2020). "DNA-based sequencing of the GJB2 gene may help identify novel mutations associated with hereditary deafness." (PMID 29773520, 2019). "The known deafness genes with variants detected in this study were GJB2 (MIM 121011; 21.2%), TMPRSS3 (MIM 605551; 6.1%), MYO15A (MIM 602666; 6.1%), TMC1 (MIM 606706; 3%), ADGRV1 (MIM 602851; 3%), PTPRQ (MIM 603317; 3%), SLC26A4 (MIM 605646; 3%), and OTOF (MIM 603681; 3%)." (PMID 31379920, 2019). "Therefore, we suggest that del(GJB6-D13S1830) testing should be performed only when patients with deafness carry the monoallelic GJB2 mutation." (PMID 30344259, 2018). "The GJB2 variant c.88A>G leads to the amino acid substitution p.I30V, and was first detected as a single allelic mutation in one patient of a cohort of 324 Taiwanese individuals with prelingual deafness." (PMID 29320412, 2018). "Indeed, low frequency of < 10% of deafness-associated GJB2 mutations has been reported in several populations with lower socioeconomic status, such as patients in Sudan, Kenya, Indonesia, and Cameroon." (PMID 30576380, 2018). "Therefore, we recommend that del(GJB6-D13S1830) testing should be performed only in patients with deafness that carry a monoallelic GJB2 mutation." (PMID 30344259, 2018). "This regimen also slowed progression of deafness for a boy with GJB2 (CONNEXIN 26) mutations." (PMID 26965868, 2016). "In previous work we investigated the molecular basis of deafness by screening GJB2 (Cx26) mutations in ethnically heterogeneous patients from the Altai Republic (South Siberia) and found variable contribution of certain mutations in GJB2 to HL in patients belonging to different ethnic groups." (PMID 27082237, 2016). "Our study also suggests that CAVs in the organ of Corti may play a crucial role in the progression or secondary pathogenesis of GJB2-associated deafness." (PMID 26492081, 2015). "Investigation of these molecular pathways, including those involving CAV2, may contribute to our understanding of the pathogenesis of GJB2-associated deafness and provide new information on effective targets for new therapies." (PMID 26492081, 2015). "Investigation of these molecular pathways, including those involving CAV2, may contribute to the elucidation of a new pathogenic mechanism of GJB2-associated deafness and identify effective targets for new therapies." (PMID 26492081, 2015). "In our previous study, two cases with heterozygous GJB2 mutations and two cases with homoplasmic 12S rRNA:A1555G mutations were identified from 92 Tibetan prelingual deafness students who underwent mutation screening for GJB2, SLC26A4, and mitochondria DNA 12S rRNA mutations." (PMID 25474651, 2014). "We identified many well-established deafness mutations (e.g., GJB2 c.235delC, GJB2 p.V37I, SLC26A4 c.919-2A > G, as well as previously un-reported novel mutations (e.g., DSPP c.3264_3265insCGATAGCGG, p.S1088delinsSRX) which we predict to be deleterious to protein functioning." (PMID 25342930, 2014). "Our results together with previous findings suggest that monoallelic GJB2 mutations may contribute to NSHL as a result of their co-inheritance with other deafness-causing genes." (PMID 25388789, 2014).
deafness (continued). "Interestingly, a population of patients exist with mutations in the GJB2 gene that encodes Cx26 representing a large population base with systemic and impaired Cx26 channels that result in deafness and skin diseases." (PMID 24988191, 2014). "Mutations in GJB2, the gene most frequently involved in autosomal recessive deafness in Tunisia, and mutations in other DFNB genes that had previously been reported in Tunisian deaf patients were first excluded by PCR and Sanger sequencing of these genes in the patients." (PMID 24926664, 2014). "After the exclusion of GJB2 mutations and other mutations previously reported in Tunisian deaf patients, we performed whole exome sequencing in patients affected with severe to profound deafness, from four unrelated consanguineous Tunisian families." (PMID 24926664, 2014). "Even if those with variants of unknown significance are excluded, the heterozygote carriership rate for SLC26A4 mutations would be almost 4 times that for GJB2, the commonest form of inherited deafness." (PMID 23965030, 2013). "The carrier frequencies of deafness-causing GJB2 mutations in our case group were 0.30% for c.35delG, 2.28% for c.109G > A, 3.19% for c.176del16, 15.50% for c.235delC, 4.71% for c.299delAT, 0.30% for c.504insGCAA, 0.30% for c.605ins46 and 0.30% for c.608TC > AA, respectively." (PMID 23826813, 2013). "The 235delC appears to be the most common deafness-causing GJB2 mutation (102/658, 15.50% )." (PMID 23826813, 2013). "Second, since deafness is associated with GJB2 and GJB3, it should be noted that the deafness associated with the SLC26A4 gene might be a consequence of digenic inheritance." (PMID 23151025, 2012). "Thus, the total carrier frequency of deafness-causing GJB2 mutations in our case group was 35.55% (48/135) at least." (PMID 23554706, 2011). "Some GJB2 gene mutations exert a selective transdominant inhibitory effect on the function of other connexins, including Cx30, that are preferentially expressed in the epidermis, skin appendages, the cornea and in deafness." (PMID 21731760, 2011). "Testing for this mutation explained deafness in 1.89% of Chinese GJB2 monoallelic patients." (PMID 21122151, 2010). "Therefore, GJB2 mutations associated with deafness may play a role in tumour suppression to some extent." (PMID 38172427, 2024). "Notably, a deafness-related missense mutation rs72474224 (p.Val37 Ile) located in the GJB2 gene showed a higher allele frequency in the southern East Asian population including HM (Yao-T:0.153; Miao-T:0.250; She-T:0.278) but a lower frequency in other populations in the world." (PMID 38475771, 2024). "GJB2, also known as connexin 26 (Cx26), forms gap junction channels, and its mutation has been found to be digenic with other genes mutation in Waardenburg syndrome, which is characterized by varying degrees of deafness and pigmentation (coloring) abnormalities in the eyes, hair, and/or skin." (PMID 37255601, 2023). "Notably, one infant with deafness-causative GJB2 c.235delC homozygous variant and one with SLC26A4 c.1229 C > T/c.1975G > C passed the two-step hearing screening in our study, while the remaining five individuals with homozygous or compound heterozygous variants failed both the hearing screenings." (PMID 36389375, 2022). "However, further investigation is required to definitively characterise whether GJB2-related deafness is caused by impaired intercellular communication, and how affected supporting cells might interact with other cell types of the sensory epithelium." (PMID 36331565, 2022). "Moreover, the present study could be conducted on other genes of deafness or other polymorphisms, including rs3751385, rs7994748, and rs7987302 of GJB2 gene and rs7322538, rs9315400, rs877098, and rs945369 of GJB6 gene." (PMID 33912482, 2021).